GBA1 (glucosylceramidase beta 1)
Diseases named in the same sentence as GBA1 in open-access papers (continued):
Sharing a sentence is not in itself a finding about the gene and the disease.
Thrombocytopenia (5 papers, 2021 to 2025). A reduction in the number of circulating thrombocytes. "Patient 3: An adult woman with a history of thrombocytopenia, easy bruising, and recurrent mucosal bleeding was diagnosed with GD1 at age 39 due to homozygosity for the p.Asn409Ser GBA1 mutation." (PMID 41282474, 2025). "Patient 17: Patient 17 was a male child who presented at age 48 with thrombocytopenia and hyperferritinemia and was diagnosed with GD1 due to a homozygous p.Asn409Ser GBA1 mutation." (PMID 41282474, 2025). "Patient 15: An adult woman of Italian ancestry presented at age 48 with thrombocytopenia and was diagnosed with GD1 due to a homozygous p.Asn409Ser GBA1 mutation." (PMID 41282474, 2025).
Anosmia (4 papers, 2018 to 2024). An inability to perceive odors. "Severe hyposmia and anosmia was evident in both GBA1 heterozygotes and homozygotes with PD." (PMID 36330429, 2022).
Huntington disease (4 papers, 2013 to 2022). Huntington disease (HD) is a rare neurodegenerative disorder of the central nervous system characterized by unwanted choreatic movements, behavioral and psychiatric disturbances and dementia. "These disorders include, among others, Parkinson's disease (PD) with SNCA, PINK1, PARK2, GBA1, and LRRK2 mutations, amyotrophic lateral sclerosis (ALS) with TDP43 mutation, Huntington's disease (HD) with HTT mutation, and Spinal muscular atrophy (SMA) with SMN1 mutation." (PMID 27313629, 2016).
Lysosomal disease (4 papers, 2019 to 2025). "CHCHD2 is the first PD-causing gene involved in the mitochondrial respiratory chain complex, and PSAP is also involved in a lysosomal disease, similar to glucocerebrosidase (GBA1)." (PMID 35821405, 2023).
Sleep disturbance (4 papers, 2022 to 2025). An abnormal pattern in the quality, quantity, or characteristics of sleep. "In GBA1 carriers, cognitive function was independent of mood and sleep dysfunction, whereas in controls, executive function was closely linked to mood and sleep." (PMID 40566604, 2025).
amyotrophic lateral sclerosis (3 papers, 2016 to 2022). Amyotrophic lateral sclerosis (ALS) is a neurodegenerative disease characterized by progressive muscular paralysis reflecting degeneration of motor neurons in the primary motor cortex, corticospinal tracts, brainstem and spinal cord. "Given previous studies demonstrating the neuroprotective and mobility effects of PGZ at 1 μM in a Drosophila model of amyotrophic lateral sclerosis, we also analyzed the effects of 1 μM PGZ treatment on locomotor activity in the GBAΔTT/ΔTT mutant flies compared to the control GBA1+/+ flies." (PMID 34884544, 2021).
COVID-19 (3 papers, 2023 to 2025). A disease caused by infection with severe acute respiratory syndrome coronavirus 2. "Lysosomal-associated membrane proteins (LAMP) and lysosomal hydrolases, mannosidases (MANBA), glucosylceramidase beta 1 (GBA), and Asp-glucosaminidases (AGA) were upregulated in COVID-19(+) cardiac tissues." (PMID 39988192, 2025). "In this work, we identified an increased expression of lysosomal genes such as LAMTOR1, NEU1, GBA1, BORCS8, and BLOC1S1 in severe COVID-19 patients." (PMID 38262689, 2024).
dysautonomia (3 papers, 2024 to 2025). An acute or chronic disorder, affecting the sympathetic or parasympathetic nervous system. "Patients with glucosylceramidase beta-1 (GBA-1) mutation, when compared with idiopathic PD, more frequently complain of cardiovascular and gastrointestinal dysautonomia." (PMID 41018272, 2025).
Gaucher disease type 2 (3 papers, 2019 to 2026). Gaucher disease type 2 is the acute neurological form of Gaucher disease (GD; see this term). "In both Gaucher disease type 2 patients and Gba1 knock out mice, epidermal abnormalities are associated with the accumulation of GC56–58." (PMID 30944381, 2019). "Notably, the decrease of Cer caused by GBA1 mutation leads to the development of Type-2 Gaucher disease (or collodion babies)." (PMID 36881564, 2023). "Similarly, glucosylceramide and glucosylsphingosine that are stored in the CNS, among other organs, in Gaucher disease type 2 and 3 caused by biallelic GVs in the GBA1 gene may act as protumorigenic agents to increase the risk of glioblastoma and other tumors." (PMID 41546701, 2026).
glaucoma (3 papers, 2019 to 2024). Increased pressure in the eyeball due to obstruction of the outflow of aqueous humor. "Further, there are reports of elevated GluSph levels in ocular tissue of glaucoma patients, suggesting an association of GBA pathway dysfunction and ocular disease even in patients without GBA1 mutations." (PMID 33727605, 2021).
glioblastoma (3 papers, 2020 to 2026). The most malignant astrocytic tumor (WHO grade IV). "Noteworthily, CRISPR/Cas9 has been successfully used for developing GD cellular models- human monocytic cell line (THP-1) with GBA1 mutation as well as glioblastoma cell line (U87) with GBA1 mutation." (PMID 38617529, 2024). "We exploited CRISPR/Cas9 technology to edit GBA1 in the human monocytic THP-1 cell line to develop an isogenic GD model of monocytes and in glioblastoma U87 cell lines to generate an isogenic GD model of glial cells." (PMID 32380730, 2020).
hereditary spastic paraplegia (3 papers, 2017 to 2024). Hereditary spastic paraplegias (HSP) comprise a genetically and clinically heterogeneous group of neurodegenerative disorders characterized by progressive spasticity and hyperreflexia of the lower limbs. "This may explain why the family member of P10, who harbored the GBA1 T408M and SPG11 Q1875* variants, showed no signs of PD nor hereditary spastic paraplegia." (PMID 38153678, 2024).
melanoma (3 papers, 2023 to 2025). A malignant, usually aggressive tumor composed of atypical, neoplastic melanocytes. "Previous studies have shown a positive association between genetically undetermined PD (GU-PD) and GBA1-PD with malignant melanoma." (PMID 41300754, 2025). "Supporting this clinical observation, studies in a type 1 GD mouse model carrying the homozygous point mutation (Gba1 D409V/D409V) demonstrated that subcutaneous injection of murine melanoma cells (B16F10) led to markedly increased tumor growth and weight compared with control littermates." (PMID 41155172, 2025). "We found only a limited number of GBA1 PD carriers with a positive cancer history (mainly skin cancer (including melanoma) and lymphomas)." (PMID 41300754, 2025).
osteoporosis (3 papers, 2023 to 2025). A condition of reduced bone mass, with decreased cortical thickness and a decrease in the number and size of the trabeculae of cancellous bone (but normal chemical composition), resulting in increased fracture incidence. "Further studies are necessary to validate the present findings and fully elucidate the mechanisms underlying the association between GBA1 variants and osteoporosis." (PMID 38575988, 2024). "This study demonstrates that variants in the GBA1 gene constitute a genetic risk factor predisposing specific populations to osteoporosis, as evidenced by the significant association between the GBA1 variant rs11264345 and reduced bone mineral density." (PMID 38575988, 2024). "Separately, our group identified a GBA1 variant increasing osteoporosis risk and found it to be associated with severe skeletal disease phenotypes, thereby linking the GBA1 genotype to bone pathology and highlighting the genetic determinants of heterogeneity." (PMID 38575988, 2024). "Through the analysis of T-scores and GBA1 sequences, we identified variants that decrease bone mineral density, thereby increasing the risk for osteoporosis and fractures." (PMID 38575988, 2024). "Further investigation showed 4 out of 6 GD patients possessing a rare GBA1 mutation (L444P) also carried the risk variant of rs11264345, evidencing a possible correlation between GBA1 mutation (L444P) and common variants elevating osteoporosis susceptibility." (PMID 38575988, 2024). "To investigate the genetic factors that may increase the risk of osteoporosis, we conducted SNPs in the GBA1 gene among individuals with Asian ancestry (N = 95,223)." (PMID 38575988, 2024). "Firstly, genetic screening for GBA1 variants may prove useful for identifying patients at higher inherent risk for osteoporosis, enabling earlier monitoring and preventative interventions before bone loss becomes severe." (PMID 38575988, 2024). "Therefore, mutation of the GBA1 gene may be one of the genetic factors in the early onset of osteoporosis." (PMID 40671914, 2025). "Furthermore, disease-associated variant in the GBA1 gene may constitute a risk factor predisposing specific populations to osteoporosis." (PMID 38575988, 2024). "A multivariate logistic regression analysis was conducted to assess the impact of GBA1 on osteoporosis." (PMID 38575988, 2024). "Our findings underscore the role of GBA1 in osteoporosis development and demonstrate the utility of PheWAS in investigating the roles of genes in complex diseases." (PMID 38575988, 2024). "This study aimed to investigate the impact of the GBA1 gene on osteoporosis progression in GD patients and the specific populations." (PMID 38575988, 2024).
progressive supranuclear palsy (3 papers, 2025 to 2026). A rare late-onset neurodegenerative disease characterized by supranuclear gaze palsy, postural instability, progressive rigidity, and mild dementia. "Searching for other cases resulted in the identification of PSEN1 p.A79V in one possible AD patient, PSEN1 p.R269H and MAPT p.A60G in two independent MCI patients, and GBA1 p.W223R and APP p.A209T in two independent progressive supranuclear palsy (PSP) patients." (PMID 40813364, 2025).
proteinopathy (3 papers, 2018 to 2023). "To elucidate novel mechanisms contributing to proteinopathy in PD, we investigated the effect of GBA1 mutations on the transcription factor EB (TFEB), the master regulator of the autophagy-lysosomal pathway (ALP)." (PMID 37332877, 2023). "Our study uncovers a new mechanism contributing to proteinopathy in GBA1-associated PD." (PMID 37332877, 2023). "Studies using human induced-pluripotent stem cells (iPSCs) harboring GBA1 mutations reported ALP dysfunction in dopaminergic (DA) neurons from PD patients and further highlighted its role in PD-associated proteinopathy." (PMID 37332877, 2023). "Our study unveils a new mechanism contributing to PD susceptibility by GBA1 mutations in which deregulation of the mTORC1-TFEB axis mediates ALP dysfunction and subsequent proteinopathy." (PMID 37332877, 2023).
breast carcinoma (2 papers, 2015 to 2022). "For example, down-regulation of GBA1 and GBA2 was found in colon cancer, whereas overexpression of GBA1 was observed in breast cancer." (PMID 35330102, 2022).
glioma (2 papers, 2023 to 2026). A benign or malignant brain and spinal cord tumor that arises from glial cells (astrocytes, oligodendrocytes, ependymal cells). "The CPGs most frequently affected by GVs were ATM in 6/206 (2.9%) families, BRCA2 in 5/206 (2.4%) families (identified in approaches 1 and 2), GBA1 in 4/206 (1.9%) families as well as EGFR, GJB2, and SDHA in 3/206 (1.5%) families each of the glioma cohort." (PMID 41546701, 2026).
Hallucinations (2 papers, 2023 to 2025). Perceptions in a conscious and awake state that, in the absence of external stimuli, have qualities of real perception. "Increased frequency and risk of psychiatric symptoms, such as hallucinations, delusions, and impulsive–compulsive behavior, has also been reported in GBA1-PD patients vs. non-carriers." (PMID 36768367, 2023).
hyperferritinemia (2 papers, 2023 to 2025). "Inherited isolated hyperferritinemia includes several rare or ultra-rare disorders caused by mutations in genes directly involved in iron metabolism (FTL, CP, SLC40A1) or not, such as GBA1." (PMID 36768886, 2023).
insomnia (2 papers, 2021 to 2023). A sleep disorder characterized by difficulty in falling asleep and/or remaining asleep. "Compared with PD patients with mild GBA1 mutations or idiopathic PD (iPD), subjects with extreme GBA1 mutations show distinctly worse motor and non-motor symptoms, such as insomnia and rapid-eye-movement (REM) sleep disturbances." (PMID 36768367, 2023).
Lipid storage disease (2 papers, 2018 to 2020). "GD is a lysosomal storage disease caused by autosomal recessive mutations in the glucocerebrosidase gene, GBA1, encoding acid beta-glucosidase, and is one of the most common lipid storage diseases (LSDs)." (PMID 30342532, 2018).
lung carcinoma (2 papers, 2015 to 2022). "It has been demonstrated previously that GBA1 acts an ACD executor in A549 lung cancer cells." (PMID 35974000, 2022). "The lysosomal enzyme GBA1 was previously identified as an ACD executor in A549 lung cancer cells." (PMID 35974000, 2022). "Therefore, we next examined whether GBA1 was involved in nutrients deprivation-induced ACD in lung cancer." (PMID 35974000, 2022).
metachromatic leukodystrophy (2 papers, 2020 to 2021). A rare lysosomal storage disorder characterized by intralysosomal accumulation of sulfatides in various tissues, leading to progressive deterioration of motor and neurocognitive function. "A retrospective study demonstrated that clinical symptoms in three families with ARSA haploinsufficiency (metachromatic leukodystrophy, or MLD) were similar to those described in PD patients with GBA1 mutations." (PMID 32674335, 2020).
Niemann-Pick disease type C (2 papers, 2021 to 2025). NPC is a complex lipid storage disease mainly characterized by the accumulation of unesterified cholesterol in the late endosomal/lysosomal compartment. "Lysosomal Ca2+ defects were reported in GBA1-linked PD building on foundational studies in models of Niemann–Pick type C disease." (PMID 40279672, 2025).
non-small cell lung carcinoma (2 papers, 2022 to 2023). A group of at least three distinct histological types of lung cancer, including non-small cell squamous cell carcinoma, adenocarcinoma, and large cell carcinoma. "Furthermore, suppression of GBA1 using siRNA induced paclitaxel resistance and the activation of the AKT pathway in three different cancer cell lines, including colon carcinoma, breast adenocarcinoma, and non-small-cell lung carcinoma." (PMID 35330102, 2022).
rest tremor (2 papers, 2024 to 2025). "In this group, 70% of GBA1-PD patients experienced symptoms before age 50 (mean age of onset: 47.8 years); 25% of these subjects noted a family history of PD; isolated rest tremor was uncommon at onset." (PMID 39766872, 2024). "70% of GBA1 patients developed symptoms before age 50, with mean age at onset of 47.8 years; a positive family history was reported in 25% of these subjects; onset with isolated rest tremor was infrequent (14% vs 36% in negative controls, p 0.02)." (PMID 39034353, 2025).
acute monocytic leukemia (1 paper, 2020). Acute monoblastic leukemia (AML-M5), is one of the most common subtypes of acute myeloid leukemia (AML) that is either comprised of more than 80% of monoblasts (AML-M5a) or 30-80% monoblasts with (pro)monocytic differentiation (AML-M5b). "Therefore, we decided to perform GBA1 editing in a human monocytic cell line deriving from an acute monocytic leukemia patient (THP-1)." (PMID 32380730, 2020).
childhood asthma (1 paper, 2019). "Susceptibility to PD and childhood asthma have been linked to genetic variants of GBA1 and ORMDL3, respectively, tying these disorders directly to the SL metabolic pathway." (PMID 30683667, 2019).
immune deficiency (1 paper, 2023). "Moreover, we show that modulation of the immune deficiency (IMD) pathway is detrimental to the survival of Gba1 deficient flies." (PMID 38127816, 2023).
lysosomal glycogen storage disease (1 paper, 2023). "In particular, we identified a class of N-alkyldeoxynojirimycins that inhibit GAA, but not GBA1, and that may form the starting point for the development of pharmacological chaperone therapeutics for the lysosomal glycogen storage disease that results from genetic deficiency in GAA: Pompe disease." (PMID 37655021, 2023).
medulloblastoma (1 paper, 2022). A malignant, invasive embryonal neoplasm arising from the cerebellum. "We therefore compared human GBA1 protein levels in a human medulloblastoma cell line with neuronal properties (Daoy cells; we will call them neurons hereafter) and a human oligodendrocyte cell line (MO3.13 oligodendrocytes; we will call them glia hereafter)." (PMID 35857503, 2022).
memory impairment (1 paper, 2016). "Memory impairments are also demonstrated in Gba1 mutant mice." (PMID 27598339, 2016).
monoclonal gammopathy (1 paper, 2023). A condition characterized by the abnormal presence of monoclonal immunoglobulins in the blood or urine. "Increased concentrations of lyso-Gb1 were identified in murine models with GBA1 gene deficiency, which was associated with monoclonal gammopathy in most cases." (PMID 36782327, 2023).
mucopolysaccharidoses (1 paper, 2023). "Moreover, the authors demonstrated that the two strongest modifiers of GBA1 penetrance were a second variation in GBA1 (5.6% vs. 1.4%) and variants in genes causing mucopolysaccharidoses (6.9% vs. 1%)." (PMID 37047309, 2023).
non-alcoholic fatty liver disease (1 paper, 2025). "CagA+ strains disrupt lipid metabolism, increasing non-alcoholic fatty liver disease, cardiovascular, and Alzheimer’s risks via PPAR interference, GBA1 demethylation, and altered FABP1/APOA1 expression, reversible by eradication." (PMID 41158522, 2025).
sensory neuropathies (1 paper, 2023). "Glucosylceramide accumulation, associated with GBA1 pathogenic variants, may contribute to PD-associated sensory neuropathies and pain." (PMID 38020640, 2023). "Low GBA1 activity has also been observed in PD patients without GBA1 pathogenic variants, indicating its involvement in developing or progressing PD-associated sensory neuropathy." (PMID 38020640, 2023). "Even in PD patients without GBA1 variants, low GBA1 activity has been observed, indicating a prevalent loss of GBA1 function that may contribute to developing or progressing PD-associated sensory neuropathy." (PMID 38020640, 2023).
neurodegenerative disease (25 papers, 2013 to 2025). A disorder of the central nervous system characterized by gradual and progressive loss of neural tissue and neurologic function. "This release pattern in GBA1-PD neurons aligns with characteristics of neurodegenerative diseases such as PD, which leads to significant loss of dopaminergic neurons and decreased DA production." (PMID 39906200, 2025). "Neuronopathic Gaucher disease (nGD) is an inherited neurodegenerative disease caused by mutations in GBA1 gene and is associated with premature death." (PMID 36204141, 2022). "α-synuclein protein aggregation and Lewy body formation are hallmark pathologic characteristics of GBA1-associated neurodegenerative diseases." (PMID 27019408, 2016). "A substantial majority (70.7%–94.8%) felt that results regarding pathogenic or likely pathogenic variants in a gene known to cause PD or other neurodegenerative diseases, as well as variants known to increase the risk of PD (e.g., GBA1 variants) should be returned." (PMID 39807215, 2024). "Thus, it is very likely, given the shared genetics, that increasing GCase lysosomal activity in the brain would be a viable therapy to restore lysosomal homeostasis in both neuronopathic GD and GBA1-associated neurodegenerative diseases." (PMID 37045813, 2023). "Moreover, the extent to which α-synuclein contributes to the pathogenesis of GBA1-associated neurodegenerative diseases also remains unclear." (PMID 27019408, 2016). "It is difficult to fully unravel the complexity of neurodegenerative diseases in cellular and animal models, so it is crucial to select appropriate GBA1-PD models according to the research objectives." (PMID 39267121, 2024). "Most GBA1 carriers were PD patients, while a subset (n=12) had other neurodegenerative diseases." (PMID 40672482, 2025).